ALB (albumin)
Diseases named in the same sentence as ALB in open-access papers (continued):
Sharing a sentence is not in itself a finding about the gene and the disease.
cancer (continued). "This strategy exemplifies a paradigm shift to precision nanomedicine in treating aggressive cancers such as TNBC by harnessing receptor‒ligand active targeting through albumin-based nanoplatforms." (PMID 41489768, 2026). "Albumin, highly concentrated in the mammalian serum, rapidly seizes the compounds and delivers them selectively to the cancer cells." (PMID 42294238, 2026). "This analysis was conducted on cancer tissue samples simultaneously administered with mannose, galactose albumin, or glucose albumin." (PMID 41355949, 2026). "BACKGROUND: As a novel inflammatory-nutritional biomarker, the C-reactive protein–albumin–lymphocyte (CALLY) index has demonstrated significant prognostic value in several cancer types." (PMID 42032543, 2026). "In contrast, galactose and glucose albumin displayed distribution patterns akin to those of cancer/epithelial cells." (PMID 41355949, 2026). "The neutrophil percentage-to-albumin ratio (NPAR) is a novel inflammatory-nutritional biomarker that has prognostic value in various cancers." (PMID 41601773, 2026). "Among the various protein-based nanocarriers, albumin has emerged as a particularly promising platform for cancer drug delivery, especially in the context of TNBC." (PMID 41489768, 2026). "Demographic data, albumin levels, comorbidities, cancer type, and active anti-cancer therapy were compared between the SP and non-pleurodesis (NP) group." (PMID 41646594, 2026). "This aligns with the systemic inflammatory response observed in cancer, where chronic inflammation drives neutrophilia while simultaneously suppressing albumin synthesis via cytokine-mediated pathways (e.g., IL-6 and TNF-α)." (PMID 40709341, 2025). "PNI, calculated from serum albumin levels and lymphocyte counts, was initially used to predict the prognosis of cancer patients." (PMID 40672827, 2025). "Key features contributing to the predictive value of the GBM included age, weight loss, Eastern Cooperative Oncology Group (ECOG) performance status, cancer biomarkers and serum markers of frailty, such as albumin and hemoglobin." (PMID 39753967, 2025). "A low HALP score, which is the combination of hemoglobin, albumin, lymphocyte and platelet counts has been shown to be another sign of poor prognosis in cancer." (PMID 40282930, 2025). "The HALP score, which encompasses crucial immune and nutritional factors, such as haemoglobin, albumin, lymphocyte count and platelet count, has demonstrated prognostic value across various cancer types." (PMID 40629172, 2025). "The Glasgow Prognostic Score, calculated from albumin values, serves as an indicator of nutrition and inflammation status in cancer patients, and is useful for predicting prognosis after chemotherapy for advanced CRC." (PMID 40447850, 2025). "The 378 (15.3%) participants who suffered disability at 180 days after surgery were older, smoked less often, were more often diagnosed with cancer and were characterised by lower preoperative levels of albumin and haemoglobin." (PMID 40891865, 2025). "In our study, both low‐serum albumin concentrations and an elevated SIRI were associated with mortality and cancer progression in univariate analyses, but only albumin remained associated with these poor cancer outcomes in multivariate analyses." (PMID 40116494, 2025). "In conclusion, the CCAR index—a composite measure of Cr, C‐reactive protein and albumin—emerges as a powerful and reliable prognostic tool for cancer cachexia." (PMID 41216846, 2025). "A 2025 methodological review catalogued >50 isolation workflows and concluded that only 14% of cancer studies simultaneously optimise recovery, purity, and yield, with polymer-precipitation samples showing up to 25% albumin carry-over." (PMID 41462940, 2025). "In recent years, the use of albumin to assess the immune status of cancer patients has gained increasing attention." (PMID 41438759, 2025).
cancer (continued). "High specificity is also preserved in differentiating THBS2 from other markers such as cancer antigen (CA) 19-9 and bovine serum albumin (BSA)." (PMID 40141965, 2025). "The researchers found that TM4SF5 helps cancer cells absorb ALB through a process called macropinocytosis, which supports energy production and cell movement." (PMID 40186033, 2025). "A meta-analysis study in older adults with cancer showed the nutritional index was based on albumin and lymphocyte counts." (PMID 40806017, 2025). "The prognostic nutritional index (PNI), derived from albumin levels and lymphocyte counts, has also been validated in various cancers, with lower PNI values indicating poorer outcomes." (PMID 40142762, 2025). "The GNRI, derived from serum albumin levels and body weight, has been widely used as a simple yet effective tool to assess nutritional status and predict survival outcomes in various cancer types." (PMID 40710183, 2025). "This study aimed to explore the prognostic relevance of the lactate dehydrogenase-to-albumin ratio (LAR) in cancer patients." (PMID 40693202, 2025). "In cell culture experiments, fluorescently labeled albumin can permeate into cancer cells and colocalize with the HMCD NIR fluorescence." (PMID 39904854, 2025). "The results indicate that alginate–albumin microcapsules can serve as an effective platform for drug delivery, especially in cancer therapy and other biomedical applications." (PMID 41465231, 2025). "PNI, calculated using the albumin level and lymphocyte count, has the potential to significantly affect the prognosis of patients with cancer." (PMID 40234099, 2025). "Among thes e genes, GAPDH exhibited upregulated expression across multiple cancer types, whereas ALB was consistently downregulated." (PMID 40463370, 2025). "Surgical resection of the cancer resulted in rapid normalization of the patient’s serum albumin level, resolution of peripheral edema, and, ultimately, successful closure of the diverting ileostomy." (PMID 41497708, 2025). "Studies have shown that KRAS-mutant cancer cells exhibit sensitivity to a variety of albumin-conjugated drugs, including adriamycin, anti-EGFR antibodies, and human β-defensin-2." (PMID 40723808, 2025). "This nanoplatform offers a new strategy for designing lymph node- and cancer-targeted albumin-based nanomedicine for clinical applications." (PMID 40908968, 2025). "Both neutrophils and albumin play crucial roles in inflammation and immune responses, with emerging evidence linking these responses to the efficacy of cancer therapies and patient prognoses." (PMID 39831739, 2025). "PNI, composed of albumin and lymphocyte counts, is a well‐established marker for nutritional status and cancer prognosis." (PMID 40631494, 2025). "Serum albumin is a commonly used marker of disease severity, an established prognostic indicator in cancer, and a tool for evaluating the efficacy of immune checkpoint inhibitors (Kuang, Miao & Zhang, 2024)." (PMID 41244206, 2025). "Various albumin-based cancer nanomedicines derived from anticancer formulations have been implemented in clinical trials, demonstrating the promise of albumin in treating cancer." (PMID 41211197, 2025). "There are also reports that albumin inhibits cancer invasion and metastasis, indicating its involvement in the progression of HCC." (PMID 41008815, 2025). "CKD stage 3 to 5 had an adjusted HR of 1.23 (95% CI: 1.16–1.30, p < 0.001), cancer had an adjusted HR of 1.17 (95% CI: 1.11–1.24, p < 0.001), and serum albumin < 4 g/dL had an adjusted HR of 1.10 (95% CI: 1.04–1.17, p = 0.001)." (PMID 41331911, 2025). "Beyond serum albumin levels alone, several albumin-based biomarkers, developed by combining albumin with other factors, have demonstrated prognostic value in cancer patients." (PMID 40741001, 2025). "Strikingly, KEGG analysis indicated that cancer‐related signal pathways were enriched in ALB+KRT7+ EPCs, such as Wnt signalling." (PMID 39834100, 2025).
cancer (continued). "Albumin, the most abundant protein in plasma, has been reported to have a negative correlation with pro-inflammatory and angiogenic cytokine levels in cancer patients." (PMID 41568390, 2025). "Despite the successfulclinical establishment of albumin-bindinganticancer drugs like Abraxane, understanding the role of albuminin cancer homeostasis and identifying biomarkers for targeted drugdelivery remains challenging." (PMID 40526060, 2025). "Their model was grounded in the understanding that the PNI—calculated from serum albumin levels and total lymphocyte count—reflects both the nutritional and immunological status of cancer patients." (PMID 40332145, 2025). "The IPTW calculation accounted for demographic information, area-level SES, insurance status, cancer characteristics, ECOG performance status, cancer-specific biomarkers, albumin, weight change at time of metastatic diagnosis and mortality risk score." (PMID 39753967, 2025). "Albumin is an important component of human plasma and can effectively reflect the nutritional and immune status of patients with cancer." (PMID 40264786, 2025). "Haemoglobin, albumin, and lymphocyte counts were lower in the cancer group compared to the control group." (PMID 40362613, 2025). "In ESCC patients, various nutritional indices such as BMI and serum albumin levels were proven to be correlated with cancer progression and prognosis; some of them have already been widely used in clinics to evaluate the nutritional level of patients." (PMID 40635897, 2025). "Nutritional Status (CONUT) score, Nutritional Risk Index (NRI), and albumin-to-globulin ratio (AGR), have emerged as potential indicators of cancer cachexia and predictors of clinical prognosis." (PMID 40133874, 2025). "Increased HR for cancer death was significant in low albumin group, and close to significant in high gamma gap group." (PMID 41248155, 2025). "Conversely, serum albumin levels typically decrease in patients suffering from cancer cachexia, reflecting the decline in nutritional status and overall health." (PMID 40469669, 2025). "Despite access to a wide range of lipid classes available in serum, we find albumin-bound lipids are the primary species consumed by cancer cells." (PMID 40930249, 2025). "Several investigators also showed that serosal invasion is related to albumin concentration in other types of cancer." (PMID 41008815, 2025). "The PNI, calculated from serum albumin levels and peripheral blood lymphocyte counts, is employed to evaluate the perioperative state and predict outcomes in patients with malignant tumors of the gastrointestinal tract." (PMID 41154405, 2025). "This review contextualizes the significance of protein-based NPs with a focus on albumin-based formulations, their clinical applications in cancer treatment, the challenges they encounter, and future possibilities for advancing this technology." (PMID 41155927, 2025). "In chronic inflammations and advanced cancers, albumin synthesis is lower, mainly under the influence of the pro-inflammatory cytokines IL-6 and TNFα." (PMID 40149324, 2025). "Several systemic inflammation markers, such as lymphocyte count and serum albumin, have been identified in various cancer types." (PMID 40641926, 2025). "Serum ALB and Hb, as fundamental plasma proteins with diverse physiological functions, have been established as reliable prognostic indicators across various cancers." (PMID 40538836, 2025). "The hemoglobin, albumin, lymphocyte, and platelet (HALP) score, associated with both inflammation and nutrition, can effectively predict prognosis in various cancers." (PMID 40538836, 2025). "The combination of albumin and inflammatory status has been demonstrated to correlate significantly with the prognosis of patients diagnosed with cancers." (PMID 41211422, 2025).
cancer (continued). "Included cohorts had data on albuminuria [urine albumin-to-creatinine ratio (ACR)], estimated glomerular filtration rate (eGFR), overall and site-specific cancer incidence, and established risk factors for cancer." (PMID 40914744, 2025). "The fibrinogen-to-albumin ratio (FAR), obtained based on routine blood test results as FAR = fibrinogen/albumin, has also demonstrated significant potential in predicting cancer prognosis." (PMID 40678069, 2025). "Examples of such systems include nanobodies–liposomes, nanobodies–micelles, and nanobody–albumin nanoparticles with increased specificity for EGFR-expressing cancer cells." (PMID 41009364, 2025). "Although previous studies have demonstrated the prognostic utility of the CRP-albumin-lymphocyte (CALLY) index in various cancer types, data regarding its role in metastatic renal cell carcinoma (mRCC) remain limited." (PMID 40836295, 2025). "In cancer patients, albumin levels often decrease due to factors like the high metabolic demands of cancer cells and nutrient competition." (PMID 39831739, 2025). "Low levels of albumin are common in patients with advanced cancer, suggesting that the body is in a state of chronic malnutrition." (PMID 40642085, 2025). "In previous studies, it has been shown that the serum albumin level is a prognostic factor in cancer." (PMID 40095884, 2025). "In cancer patients, serum albumin remains clinically indispensable for assessing nutritional status, disease severity, progression, and prognosis." (PMID 40869526, 2025). "Serum albumin and cholesterol levels are key nutritional indicators, and studies have related poor nutrition to poor cancer prognosis." (PMID 40870429, 2025). "Many studies have shown that low ALB levels are an independent indicator of poor survival in various cancers." (PMID 40896424, 2025). "In advanced cancer, increased inflammation leads to increased neutrophils, reduced lymphocytes, and lower albumin levels, which can suppress cancer immunity and diminish ICI efficacy, possibly explaining the lower irAE incidence in patients with reduced PNI." (PMID 40040713, 2025). "The PNI, which consists of nutritional (serum albumin level) and immunological (lymphocyte count) indices, is widely used as a predictive indicator of postoperative morbidities and mortality in cancer patients." (PMID 40566117, 2025). "The serum albumin level serves as an indicator of the inflammatory and nutritional status in patients with malignant tumors." (PMID 39979915, 2025). "Altogether, the preference for albumin-bound lipids during proliferation across various cells suggests that these lipids fulfill a general metabolic requirement for cancer cell proliferation in culture." (PMID 40027810, 2025). "Additional studies have further corroborated that low serum albumin predicts higher cancer-related mortality." (PMID 41586228, 2025). "The integration of nanotechnology into cancer treatment, as exemplified by formulations, such as paclitaxel bound to albumin and PLD, has demonstrated improved therapeutic outcomes across various malignancies." (PMID 40697515, 2025). "This study aimed to investigate the link between abnormal calcium and albumin levels and subsequent cancer diagnosis in patients of different ethnic groups consulting in English primary care." (PMID 40941010, 2025). "The PNI, which incorporates serum albumin levels and lymphocyte count, has been shown to correlate with survival rates and disease prognosis in patients with various conditions, including cancer, cardiovascular diseases, and chronic illnesses." (PMID 40507116, 2025). "Regarding inflammatory-related indicators, albumin levels in the cancer group (4.19 ± 0.33 g/dL) demonstrated significantly reduced levels relative to the non-cancer group (4.33 ± 0.33 g/dL) (P < 0.001)." (PMID 40531914, 2025).
cancer (continued). "GNRI is calculated using serum albumin levels and body weight and serves as an indicator of nutritional status and frailty, both of which are critical in cancer outcomes." (PMID 39840727, 2025). "Thirdly, cancer cells exhibit increased uptake of albumin via macropinocytosis to support their rapid multiplication and growth." (PMID 41142425, 2025). "Current understanding of low serum albumin in cancer is the result of a combination of increased vascular permeability, increased degradation/decreased albumin half-life, and a decreased distribution volume throughout the body." (PMID 40103850, 2025). "Specifically, NMI was shown to bind MAOA and the blood carrier protein, albumin, providing insights to image and treat cancer." (PMID 39904854, 2025). "Serum albumin, a crucial nutritional indicator, is widely acknowledged as a significant prognostic factor for numerous cancers." (PMID 40936483, 2025). "Univariate analysis revealed that age, CXI, SMI, serum ALB, NLR, ECOG PS, TNM Stage, and surgery were significantly associated with overall survival (OS) in patients with cancer cachexia (p < 0.05)." (PMID 41586248, 2025). "Due to its microtubule’s interaction, ALB recently has been showing great potential as repurposed anti-cancer drug." (PMID 40978467, 2025). "Other drug delivery systems, such as poly-(methyl methacrylate, or PMMA) nanoparticles, conjugated with albumin to enhance biocompatibility, present significant potential in cancer therapy." (PMID 40699702, 2025). "The decrease in serum albumin levels is a marker of poor nutritional state and systemic inflammation, both being vital in the prognosis of cancer." (PMID 41200633, 2025). "The research has found that arginine can significantly increase the albumin level and lymphocyte count of cancer patients, reduce the incidence of postoperative infections, and shorten the hospital stay." (PMID 41040673, 2025). "Hemoglobin levels were significantly lower in the cancer group (10.5 [9.2–12.2] vs. 13.9 [13.2–14.9] g/dL, p < 0.001), as were total serum proteins (6.1 [5.4–6.7] vs. 6.9 [6.6–7.4] g/dL, p < 0.001) and albumin (3.4 [2.9–3.9] vs. 4.2 [3.8–4.5] g/dL, p < 0.001)." (PMID 40299527, 2025). "Immune cells, including neutrophils, lymphocytes, and monocytes, along with nutritional markers, such as albumin and cholesterol, are useful for predicting cancer prognosis." (PMID 40870429, 2025). "Yet established formulations like Taxol (Cremophor EL‐based paclitaxel) and Abraxane (albumin‐bound paclitaxel) are widely used and serve as standard treatments in various cancers." (PMID 40693742, 2025). "The neutrophil-percentage-to-albumin ratio is a recently developed marker and, like other similar inflammatory markers, was first used in studies to evaluate cancer patients." (PMID 40428737, 2025). "Albumin is known to be internalized by cancer cells through the gp60 receptor, which is overexpressed at the surface of many cancer cells, including U87 MG cells." (PMID 40867175, 2025). "Existing literature has extensively documented alterations in plasma components such as cholesterol and albumin in cancer patients compared to healthy individuals." (PMID 41226320, 2025). "Inflammatory cytokines associated with cancer, including interleukin-6 (IL-6), interleukin-1, and tumor necrosis factor-alpha (TNF-α), suppress albumin synthesis and contribute to the development of cancer cachexia." (PMID 40786260, 2025). "Biological assessments reveal low haemolytic potential, effective anti‐inflammatory activity via the inhibition of thermal‐induced albumin denaturation, selective cytotoxicity against cancer cells, and broad‐spectrum antimicrobial effects." (PMID 39417784, 2025). "The serum albumin level is a widely used indicator for nutritional status and disease status of cancer patients." (PMID 40566117, 2025).